XRCC2 (X-ray repair cross complementing 2)
Diseases named in the same sentence as XRCC2 in open-access papers (continued):
Sharing a sentence is not in itself a finding about the gene and the disease.
breast carcinoma (continued). "To evaluate the contribution of RAD51, XRCC3, and XRCC2 mutations to breast cancer predisposition, we screened 182 familial Finnish breast or ovarian cancer patients for germline variation in the RAD51 and XRCC3 genes and 342 patients for the XRCC2 gene." (PMID 25918678, 2015). "Previously, XRCC2 p.(Arg188His) has been associated with poor breast cancer survival but in our study, no survival effect was found for this variant or for the XRCC3 p.(Thr241Met) variant." (PMID 25918678, 2015). "XRCC2 mutations were then detected in breast cancer families but a subsequent population-based study failed to confirm an association between XRCC2 variants and breast cancer risk." (PMID 24139550, 2013). "However, there were some approvals on the connection of polymorphism in XRCC2 R188H and the risk of breast cancer before, which has not been confirmed in two population studies in the United States and Poland and several case-control experimental studies." (PMID 36761956, 2023). "The relationship between the XRCC2 R188H polymorphism and breast cancer was not obvious." (PMID 36761956, 2023). "In addition, previous studies support our findings, reports suggest that overexpression of XRCC2 in rectal cancer predicts higher malignancy and more lymphatic metastasis and that abnormal overexpression of XRCC2 predicts poor prognosis in breast cancer patients." (PMID 34051735, 2021). "Our analysis suggests that mutations of XRCC2 do not confer elevated breast cancer risk." (PMID 31463769, 2019). "In conclusion, the absence of mutations among breast cancer families and similar distribution of haplotypes between breast cancer cases and controls suggests that RAD51, XRCC3, and XRCC2 do not substantially contribute to familial breast cancer predisposition in the Finnish population." (PMID 25918678, 2015). "The role of -41657C/T variation of XRCC2 in breast cancer is still unknown." (PMID 25743260, 2015). "Since XRCC2 gene is a key mediator in homologous recombination pathway, XRCC2 mutation carriers may benefit from specific targeted therapies such as PARP-inhibitors, but the actual influence of XRCC2 mutations on breast cancer susceptibility requires further investigation." (PMID 23586058, 2013). "Somatic homozygous deletion, labeled as deep deletion, were observed in BRCA2 in a single breast cancer patient and in pancreatic cancer (RAD51B (n = 2), RAD51C (n = 2) and XRCC2 (n = 1))." (PMID 35783256, 2022). "A homozygous XRCC2 mutation has also been detected in a Fanconi anemia patient and rare mutations in the gene in breast cancer families were identified in an exome sequencing study; however, the association of XRCC2 with breast cancer risk could not be confirmed in a large follow-up study." (PMID 27149063, 2016). "Genetic variability in DNA double-strand break repair genes such as RAD51 gene and its paralogs XRCC2、XRCC3 may contribute to the occurrence and progression of breast cancer." (PMID 36761956, 2023). "We believe the data generated might be of relevance to other researchers involved in delineating the functional mechanisms of SNPs located in the 3′UTR of the XRCC2 and PHB breast cancer related genes." (PMID 30180900, 2018). "To date, no studies have been conducted on breast cancer-driven genes such as ATM, PALB2, CHEK2, and XRCC2 reported from the Khyber Pakhtunkhwa region or Pashtun ethnicity and their potential associations with the various clinicopathologic and hormonal characteristics." (PMID 38784039, 2024). "To clarify whether XRCC2 expression is abnormal in human colon cancer, we analyzed XRCC2 expression in various tumor cell lines (colon cancer cell lines T84, HT29 and Lovo, breast cancer cell line MCF-7, esophageal cancer cell line EC9706) and normal HEK293 cell line." (PMID 24481064, 2014).
ovarian carcinoma (20 papers, 2009 to 2024). A malignant neoplasm originating from the surface ovarian epithelium. "The presented studies, carried out within the population of Polish women, confirmed the relationship of the studied XRCC2 gene polymorphism to the development of ovarian cancer." (PMID 30712190, 2019). "We found borderline evidence of a decrease in ovarian cancer risk associated with the XRCC2 variant rs3218536 using a log-additive model in the original data provided by six OCAC sites (OR=0.89, 95% CI 0.78–1.02, P=0.095) with 2763 cases and 5479 controls." (PMID 19127255, 2009). "In ovarian cancer, XRCC2 expression also directly associates with OS and PFS." (PMID 36293346, 2022). "Interestingly, one Fanconi anemia patient has been found to carry a homozygous truncating XRCC2 mutation while biallelic mutations in four breast and ovarian cancer susceptibility genes, BRCA2, BRIP1, PALB2, and RAD51C, are associated with Fanconi anemia." (PMID 25918678, 2015). "Previous studies suggested that XRCC3 rs861539, XRCC2 rs718282, XRCC2 rs3218536, BRCA1 rs1799950, RAD51 rs1801320 and LIG4 rs10131 were associated with the risk of ovarian cancer." (PMID 38890669, 2024). "In this study, higher expression of XRCC2 mRNA and protein levels was observed in normal cells than that in ovarian carcinoma cell lines." (PMID 34539898, 2021). "Our results discovered that elevation of XRCC2 and XRCC9 expression was linked to the favorable PFS and OS in all ovarian carcinoma patients." (PMID 34539898, 2021). "Significantly elevated protein levels of XRCC2 were observed in healthy control tissues, while they were rarely expressed in ovarian cancer tissues, the mean IHC score was 7.93±2.87 in normal ovarian tissues and 2.40±2.13 in ovarian cancer tissues, P<0.0001." (PMID 34539898, 2021). "Recent studies explored XRCC2 rs3218536 and ERCC2 rs13181 polymorphisms and ovarian cancer (OC) risk." (PMID 27863412, 2016). "The present study analysed the five RAD51 paralogs (RAD51B, RAD51C, RAD51D, XRCC2, XRCC3) to estimate their contribution to breast and ovarian cancer predisposition." (PMID 24139550, 2013). "In this study, we analysed the five RAD51 paralogs (RAD51B, RAD51C, RAD51D, XRCC2, XRCC3) in 142 unrelated patients with breast and/or ovarian cancer to estimate their contribution to breast and ovarian cancer predisposition." (PMID 24139550, 2013). "Recent studies conducted on RAD51 paralogs, involved in the same DNA repair pathway, have identified rare germline mutations conferring breast and/or ovarian cancer predisposition in the RAD51C, RAD51D and XRCC2 genes." (PMID 24139550, 2013). "Along with SNPs in two other NER proteins, XRCC1 and XRCC2, the XPC Ala499Val polymorphism was found to correlate to a decreased odds of ovarian cancer (OR 0.35) while the XPC Lys939Gln polymorphism was associated with an increased risk of ovarian cancer (OR 1.72) in a dominant genetic model." (PMID 35530314, 2022). "In contrast to ovarian cancer, XRCC2 expression inversely correlates with glioma patient prognosis." (PMID 36293346, 2022). "To date, our findings display the expression level and predictive value of XRCC2 in ovarian carcinoma, implying that XRCC2 might be a favorable prognostic indicator for ovarian cancer, particularly in patients with serous, poor-differentiated and late stage." (PMID 34539898, 2021). "However, high level of XRCC2 was found to be involved in a poor PFS in stage I+II ovarian carcinoma patients (HR=2.11 (1.19-3.76), P=0.0093)." (PMID 34539898, 2021). "Up-regulation of XRCC2 and XRCC9 was dramatically correlated with favorable PFS and OS for all ovarian carcinoma patients (XRCC2, PFS: HR=0.81 (0.71-0.93), P=0.0029; OS: HR=0.83 (0.72-0.96), P=0.014; XRCC9, PFS: HR=0.83 (0.73-0.95), P=0.0061; OS: HR=0.83 (0.73-0.95), P=0.0051)." (PMID 34539898, 2021). "Additionally, when compared to ovarian carcinoma cell lines, elevated mRNA and protein levels of XRCC2 and XRCC9 were detected in normal ovarian cells." (PMID 34539898, 2021).
ovarian carcinoma (continued). "Moreover, elevated XRCC2 mRNA level was also linked to better PFS for patients with serous ovarian carcinomas, better PFS and OS for patients with grade III and stage III+IV ovarian carcinomas." (PMID 34539898, 2021). "However, XRCC2 might have diverse roles in progression and tumorigenesis of ovarian carcinoma, and the results of previous researches were inconsistent." (PMID 34539898, 2021). "In summary, this study illustrated that elevated mRNA and protein levels of XRCC2 and XRCC9 were obviously detected in normal ovarian cells or tissues than that in ovarian carcinoma cells or tissues." (PMID 34539898, 2021). "Consistently, immunofluorescence analysis observed higher staining of XRCC2, XRCC4 and XRCC9 in normal ovarian IOSE cells than that in ovarian carcinomas ES2 cells and OVCAR3 cells." (PMID 34539898, 2021). "The results displayed that XRCC2, XRCC4 and XRCC9 mRNA levels were highly expressed in normal ovarian IOSE cells than in ovarian carcinoma ES2 and OVCAR3 cells." (PMID 34539898, 2021). "For example, in ovarian cancer, MRPL15 (mitochondrial ribosomal protein 15) is suggested as a prognostic indicator and therapeutic target, or XRCC2 repairing mtDNA damage in hepatocellular carcinoma." (PMID 35008363, 2021). "Increased XRCC2 showed a prolonged PFS in ovarian carcinoma patients with grade I (HR=0.17 (0.05-0.56), P=0.0009), as well as a better PFS and OS in grade III ovarian carcinoma patients (PFS: HR=0.76 (0.63-0.91), 0.0026; OS: HR=0.8 (0.67-0.96), P=0.016)." (PMID 34539898, 2021). "Then, higher staining levels of XRCC2 and XRCC9 were discovered in healthy control tissues than that in ovarian carcinoma tissues." (PMID 34539898, 2021). "With these in mind, only XRCC2, XRCC4 and XRCC9 exhibited consistent results in PFS and OS for all ovarian carcinoma patients." (PMID 34539898, 2021). "Elevated mRNA of XRCC2 was also correlated with better PFS in patients with serous ovarian carcinomas, and better PFS and OS in grade III and stage III+IV ovarian carcinomas patients." (PMID 34539898, 2021). "Consistently, higher staining of XRCC2 and XRCC9 was also detected in normal ovarian cells than that in ovarian cancer cells." (PMID 34539898, 2021). "Mutations in the human RAD51 paralogs (RAD51B, RAD51C, RAD51D, XRCC2, XRCC3, and SWSAP1) are found in a subset of breast and ovarian cancers." (PMID 30551670, 2018). "A number of the RAD51 mediators have now been added to the more comprehensive breast and ovarian cancer screening panels (i.e., PALB2, RAD51C, RAD51D, XRCC2)." (PMID 30551670, 2018). "Notably, the protein level of XRCC2 and XRCC9 were found to be overexpressed in normal ovarian tissues, whereas XRCC4 was highly expressed in patients with ovarian carcinoma, which was consistent with the prognosis of ovarian cancer." (PMID 34539898, 2021). "Furthermore, XRCC2 and XRCC9 showed favorable predictive values in ovarian carcinoma, especially in patients with serous, poor-differentiated and late-stage." (PMID 34539898, 2021). "In the scope of the German Consortium for Hereditary Breast and Ovarian Cancer, other candidate genes (e.g., NBN, FANCM, XRCC2, and RECQL) are currently co-analyzed for research purposes and their significance in contributing to breast and ovarian cancer is under investigation." (PMID 34680878, 2021). "Additionally, the protein levels of XRCC2, XRCC4 and XRCC9 were also showed higher expression in IOSE cells as compared with ES2 and OVCAR3 ovarian cancer cells, which was corresponding to the results of mRNA." (PMID 34539898, 2021). "Furthermore, XRCC2, XRCC4 and XRCC9 displayed elevated mRNA and protein levels in normal ovarian cell line, as compared to ovarian carcinoma cell lines." (PMID 34539898, 2021).
ovarian carcinoma (continued). "A significant correlation was revealed between single nucleotide polymorphisms of DNA double-strand break repair genes via homologous recombination (HR) XRCC3-Thr241Met (rs861539), XRCC2--41657C/T (rs718282), BRCA1-Q356R (rs1799950) and RAD51–135 G/C (rs1801320) and ovarian cancer development." (PMID 30712190, 2019).
Fanconi anemia (18 papers, 2015 to 2025). Fanconi anemia (FA) is a hereditary DNA repair disorder characterized by progressive pancytopenia with bone marrow failure, variable congenital malformations and predisposition to develop hematological or solid tumors. "The genes FANCM, FANCA and XRCC2 are also directly involved in the Fanconi anaemia pathway, as biallelic variants in these genes can cause Fanconi anaemia." (PMID 39257928, 2024). "Mutations in RAD51C and XRCC2 result in Fanconi anemia, a syndrome associated with extreme sensitivity to drugs like mitomycin C (MMC) that induce DNA interstrand crosslinks." (PMID 31584931, 2019). "TONSL knockdown significantly reduced the expression of FANCD1 and XRCC2, both key players in the Fanconi anemia and homologous recombination repair pathways, while DDB2 and NEIL3 showed no statistically changes." (PMID 39944694, 2025). "Deficiency in several of the classical human RAD51 paralogs [RAD51B, RAD51C, RAD51D, XRCC2 and XRCC3] is associated with cancer predisposition and Fanconi anemia." (PMID 31584931, 2019). "Examples of disorders we were able to confirm through this approach in this study are TBXT-related myelomeningocele,36APC-related Cenani–Lenz syndrome, and XRCC2-related Fanconi anemia." (PMID 30237576, 2019). "Severe sensitivity to crosslinking agents is a defining feature of cells derived from Fanconi anemia (FA) patients and unsurprisingly, RAD51C (FANCO) and XRCC2 (FANCU) mutations have been uncovered in FA or FA-like patients." (PMID 30551670, 2018). "Two genes in the HRR pathway, RAD51, and XRCC2, cell cycle regulation (CHEK2), and Fanconi Anemia (UBE2T) were significantly upregulated in Groups 3 and 4 (p = 0.042, p = 0.0042, p = 0.021, and p = 0.023, respectively)." (PMID 37334114, 2023). "These genes include the Fanconi anemia pathway genes: FANCA, PALB2, BRIP1, RAD51C and XRCC2 and non-Fanconi anemia genes: ATM, CHEK2, NBN, RAD50, RAD51B, and RAD51D." (PMID 28202063, 2017).
colorectal cancer (17 papers, 2011 to 2024). A primary or metastatic malignant neoplasm that affects the colon or rectum. "In case of Bangladeshi population, no report is observed till now showing the genetic variations of RAD51 (rs1801320) and XRCC2 (rs3218536) genes polymorphism having association with colorectal cancer risk." (PMID 32458654, 2020). "A Polish case-control study was outlined that polymorphism of the RAD51 can alter the colorectal cancer risk alone as well as with association with other polymorphisms: XRCC2 gene." (PMID 32458654, 2020). "We, consequently, presume to find out that predictable relationship of RAD51 (rs1801320) and XRCC2(rs3218536) genetic polymorphisms with colorectal cancer risk in Bangladeshi citizenry for the very first time." (PMID 32458654, 2020). "So, the association of RAD51 (rs1801320) and XRCC2 (rs3218536) genes polymorphism with colorectal cancer risk is observed in Bangladeshi population." (PMID 32458654, 2020). "So, it can be said that a significant association between RAD51 (rs1801320) and XRCC2 (rs3218536) and colorectal cancer development is confirmed in our population." (PMID 32458654, 2020). "Here we tested the hypothesis that XRCC2 loss sensitizes colorectal cancer (CRC) to PARP inhibitor in combination with radiotherapy (RT)." (PMID 35643812, 2022). "A possibility may arise basing on a correlation between RAD51 (rs1801320) and XRCC2 (rs3218536) polymorphisms with colorectal cancer risk in Bangladeshi population." (PMID 32458654, 2020). "Interestingly, in colorectal cancer patients, where high levels of SIM2s are linked to poor prognosis, high levels of XRCC2 are also associated with poor clinical outcome." (PMID 31775907, 2019). "Therefore, XRCC2 polymorphisms may take part dominant role in colorectal cancer tumorigenesis, conferring susceptibility to rectal tumors in Polish population." (PMID 32458654, 2020). "Therefore, RAD51(rs1801320) and XRCC2 (rs3218536) genes polymorphism and colorectal cancer risk is an important research area that needs much more attention as some statistically strong risk factors required to be excluded because of a small number of sample and control." (PMID 32458654, 2020). "X-ray irradiation induces XRCC2 expression in colorectal cancer cells and exhibits a dose- and time-dependent relationship between XRCC2 expression and radiation exposure." (PMID 37679817, 2023). "Downregulation of XRCC2 expression inhibits the proliferation of colorectal cancer cells and increases their sensitivity to radiation." (PMID 37679817, 2023). "The second-ranked statistically most significant downregulated miRNA, miR-7a/miR-7, also a geromiR, inhibits colorectal cancer cell proliferation and induces apoptosis by targeting XRCC2." (PMID 34062897, 2021). "In summary, studying SNP in RAD51 (rs1801320) and XRCC2 (rs3218536) genes helps to recognize the malfunction of these proteins and can lead to successful therapies for colorectal cancer." (PMID 32458654, 2020). "Taken together, these results confirm that XRCC2 expression contributes to radioresistance in colorectal cancer cells." (PMID 26320178, 2015). "XRCC2 had been shown to participate in chemoresistance to 5-Fluorouracil in colorectal cancer." (PMID 32258128, 2020). "Using multigene panel testing, we found several novel germline mutations that have been rarely reported in hereditary colorectal cancer (e.g., ERCC4, SDHA, and XRCC2), but our limited sample size hindered us from determining their penetrance and relationship with colorectal cancer." (PMID 33194656, 2020). "In our previous study, XRCC2 overexpression was found to inhibit colorectal cancer cell apoptosis." (PMID 26320178, 2015).
colorectal cancer (continued). "In addition, we previously demonstrated that XRCC2 is overexpressed in colorectal cancer tissues and cell lines." (PMID 26320178, 2015). "The present study aimed to investigate the association between X-ray repair complementing defective repair in Chinese hamster cells 2 (XRCC2) SNPs and colorectal cancer (CRC) cell sensitivity to the poly(ADP-ribose) polymerase (PARP) 1 inhibitor olaparib (AZD2281)." (PMID 25120693, 2014). "Therefore, knockdown of XRCC2 in colorectal cancer cells may activate Chk2-Thr68, thereby leading to G2/M cell cycle arrest and improved radiosensitivity." (PMID 26320178, 2015).